RN7SL189P (RNA, 7SL, cytoplasmic 189, pseudogene)
Gene: Miscellaneous RNA gene on chromosome 14 (20,963,579 to 20,963,867, forward strand). Ensembl gene ENSG00000243817.
Homologues: Orthologues: chimpanzee Metazoa_SRP (100% identical), macaque Metazoa_SRP (94% identical). Paralogues in human: RN7SL1 (80% identical), RN7SL2 (80% identical), RN7SL126P (79% identical), RN7SL3 (79% identical), RN7SL122P (78% identical), RN7SL478P (78% identical), RN7SL786P (78% identical), RN7SL45P (77% identical), RN7SL709P (77% identical), Metazoa_SRP (77% identical), RN7SL655P (77% identical), RN7SL678P (77% identical), and 703 more.